ATM (ATM serine/threonine kinase)
Diseases named in the same sentence as ATM in open-access papers (continued):
Sharing a sentence is not in itself a finding about the gene and the disease.
breast cancer (continued). "An inherited mutated copy of ATM confers an increased risk of developing breast cancer as well as pancreatic, prostate, colon, and other cancers." (PMID 33580144, 2021). "Several mutant proteins, lacking ATM kinase activity, showed a dominant negative effect like the one with the breast cancer mutation ATM S2592C." (PMID 34771661, 2021). "BARD1 (OR: 3.1, 95% CI: 1.3–7.2); CHEK2 (OR: 2.5, 95% CI:1.4–4.6); RAD51D (OR: 2.2, 95% CI: 1.3–3.8); and ATM (OR: 2.1, 95% CI: 1.2–3.6) were classified as moderate risk breast cancer risk genes." (PMID 34606182, 2021). "The pooled estimate of crude odds ratio between ATM and risk of breast cancer was 2.27 (95% CI: 1.17–4.40; I square: 74.56%; PI square: 0.0001)." (PMID 33402103, 2021). "Of note, increased ATM function has been found to be associated with elevated metastasis, invasion, and Epithelial-Mesenchymal Transition of breast cancer cells that overexpress HOXB9 or under-express PRSS11." (PMID 34070860, 2021). "Breast cancer risk estimates for women carrying other pathogenic variants in ATM have been consistently reported to be in the order of 2–3-fold." (PMID 34887416, 2021). "This study aimed to demonstrate and analyze the relationship between ATM gene polymorphisms and breast cancer prevalence rate." (PMID 34493284, 2021). "This suggests that ATM variants have a greater impact on the risk of breast cancer in the Asian population than in the European and American populations." (PMID 33402103, 2021). "Ataxia telangiectasia-mutated (ATM) gene contributes to repair damaged DNA and to regulate cell cycle; therefore, ATM variants seem to increase breast cancer risk; however, the results are controversial." (PMID 33402103, 2021). "Similar results were found through a screening of 65,057 white woman with breast cancer where a high or moderately increased risk of disease was found in relation with pathogenic mutations in ATM, CHEK2, PALB2, and RAD51D." (PMID 34299313, 2021). "Individuals carrying heterozygous pathogenic variants of ATM have a 33% cumulative lifetime risk of breast cancer by 80 years of age." (PMID 33800556, 2021). "The meta-analysis on the adjusted case-control studies revealed that ATM D1853V missense variant has the least association with an increased risk of breast cancer." (PMID 33402103, 2021). "For 31 hormone receptor (HR)+/HER2− breast cancers, there were two clusters: One with the co-occurrence of ATM, FGFR1, and WT1 frameshift mutations, and the other with JAK3 splice site and FGFR2 frameshift mutations." (PMID 34203389, 2021). "Given that ATM loss of function variants are estimated to be associated with only a modest risk of breast cancer (OR 3.0, 95% CI 2.1–4.5), larger well-designed studies will be required to determine if ATM variation confers a similar modest level of risk to EC." (PMID 33917078, 2021). "This statistical analysis indicates that heterozygous ATM variants are the most associated with breast cancer incidence." (PMID 33402103, 2021). "Moderate penetrance breast cancer susceptibility gene mutations such as PALB2, CHEK2, ATM occur in 4-6% of breast cancer patients." (PMID 34422626, 2021). "Gene body hypermethylation of ATM, a breast cancer susceptibility gene that codes for downstream signaling proteins for cell cycle arrest, can lead to the early onset of breast cancer in women, and thus is a very useful biomarker." (PMID 34576196, 2021). "ATM-heterozygous alterations are postulated to be predispose to epithelial neoplasia, in particular breast cancer and a higher rate of lymphoid malignancies are also in the focus of discussion." (PMID 34267759, 2021). "From the 9 unadjusted case control studies, the association between ATM variants and the breast cancer risk ranged between 0.37 and 12.70." (PMID 33402103, 2021). "It was additionally estimated that heterozygous carriers of ATM mutations have a two-fold higher risk of breast cancer." (PMID 33662042, 2021).
breast cancer (continued). "An example is the ATM gene that is involved in ataxia teleangiectasia in children and susceptibility to breast cancer in women." (PMID 34061292, 2021). "The results of Egger’s test showed there isn’t a publication bias in the association between ATM and risk of breast cancer (Coefficient = 2.08; P = 0.193; % 95 CI: − 0.56 – 3.16)." (PMID 33402103, 2021). "Some studies have reported an association of ATM gene mutations with breast cancer, and some have evaluated the prevalence of this gene variant in breast cancer." (PMID 34493284, 2021). "In 1996, the association of Ataxia–telangiectasia gene (ATM) mutation heterozygosity with breast cancer risk was reported from New York." (PMID 34493284, 2021). "Blood DNA hypermethylation of an intragenic locus in ATM, a breast cancer predisposition gene, was also found to be associated with increased risk of breast cancer." (PMID 34943892, 2021). "This meta-analysis shows that the pathogenic ATM variants are associated with an increased risk of breast cancer." (PMID 33402103, 2021). "Deleterious germline variants in ATR and ATM were also associated with HRD phenotype in breast cancer, ATM in prostate, lung, and stomach cancers, and BRCA2 in stomach cancers." (PMID 34572800, 2021). "This meta-analysis showed that there is a significant relationship between ATM variants in breast cancer patients." (PMID 34493284, 2021). "A meta-analysis has assessed the relationship between specific polymorphisms of ATM and the type of cancer: the ATM rs664143 polymorphism is associated with lung cancer risk, and the ATM rs664677 polymorphism is associated with a high risk of breast cancer." (PMID 33918597, 2021). "Single CFTR mutation carriers are more susceptible to cystic fibrosis-related conditions, and monoallelic ATM mutation carriers have higher risks for cancers and ischemic heart disease—especially breast cancer in female carriers." (PMID 33448283, 2021). "The pooled risk ratio between ATM variants and risk of breast cancer was 1.68 (95% CI: 1.17–2.40; 0.032; I square: 62.1%; PI square: 0.105)." (PMID 33402103, 2021). "Six individuals with breast cancer harboured risk factor variants in the ATM or CHEK2 genes, and if they had close relatives with breast cancer, they would have been offered clinical genetic testing according to guidelines." (PMID 34711244, 2021). "Accordingly, ATM variants, including V2424G have the highest risk of breast cancer incidence while ATM D1853V, L546V, and S707P variants have the least impact on breast cancer incidence." (PMID 33402103, 2021). "The pooled estimate odds ratio after synthesis results of 7 Adjusted case control studies shows that the association between ATM and risk of breast cancer was 1.67 (95% CI: 0.73–3.82; I square: 90.85%; PI square: 0.0001)." (PMID 33402103, 2021). "Further studies in BRCA2 or ATM deficient ovarian cancer or breast cancer models will be required to confirm our preliminary observations." (PMID 34373746, 2021). "As the same as our findings, all these studies emphasized that there is a strong association between ATM variants and the risk of breast cancer development." (PMID 33402103, 2021). "The ATM variants are associated with an increased risk of breast cancer that ATM V2424G mutation is detected as the most predisposing factor while ATM D1853V, L546V, and S707P variants have the least predictive ability." (PMID 33402103, 2021).
breast cancer (continued). "So we conducted a systematic review and meta-analysis to clarify the pooled association between various ATM variants and the risk of breast cancer." (PMID 33402103, 2021). "An example of this phenomenon is exemplified by ATM, an intermediate-risk breast cancer susceptibility gene that has been implicated in melanoma susceptibility." (PMID 34262154, 2021). "Another study reported that regardless of the common A-T mutation, substitution and especially missense mutations are the most common ATM variants in breast cancer patients." (PMID 34493284, 2021). "Different studies on the ATM variants and the prevalence of breast cancer have been undertaken in northern Europe." (PMID 34493284, 2021). "Another study discusses considerably low risk for breast cancer and clinical radiosensitivity but suggests that there is some threshold for the ATM protein leading to a high risk of radiosensitivity for breast cancer patients." (PMID 35054413, 2021). "Another objective of our study was to investigate the association of ATM variants with breast cancer in different regions." (PMID 33402103, 2021). "We aimed to undertake a systematic review and meta-analysis of the prevalence of ATM variants in breast cancer from different countries, the association of these variants with the BRCA status of patients, and the prevalence of other variants in the ATM gene." (PMID 34493284, 2021). "In particular, families carrying heterozygous germ-line variants of ATM gene have a 5- to 9-fold risk of developing breast cancer." (PMID 33494414, 2021). "Mutations in ATM, which is a well characterized tumor suppressor has been associated with oral cancer, lung cancer and breast cancer." (PMID 34796107, 2021). "The results of the current study indicate that ATM missense variants increase the incidence of breast cancer and people who carry these variants have an increased risk of developing breast cancer." (PMID 33402103, 2021). "The patient II.5, diagnosed with breast cancer at the age of 43, carried the ATM variant c.3663G > A. Her family had, on the paternal side, two very early cancer cases at 25 (I.10) and 36 (I.11) years-old." (PMID 32756499, 2020). "Family members with a single ATM mutation have an increased risk for developing cancer (especially breast cancer in women) and cardiovascular diseases." (PMID 31709473, 2020). "Top clock CpGs negatively associated with age and their annotated genes are enriched in ATM and apoptosis signaling, both of which are linked to genome integrity and aging as well as sustaining breast-cancer tumorigenicity and tumor morphology." (PMID 32164769, 2020). "In contrast, increases in ATM signaling have been linked to radiation resistance of breast cancer cells, and inhibition of ATM kinase activity using KU55933 sensitized tumor cells to radiation and chemotherapy." (PMID 33338048, 2020). "In fact studies conducted so far show that the only solid tissue malignancy that ATM heterozygote carriers have high risks for is breast cancer and the risk, if any, is moderate." (PMID 32566127, 2020). "For example, ATM, a rare moderate-penetrance breast cancer susceptibility gene, is responsible for phosphorylation and chromatin recruitment in FANCM." (PMID 32300589, 2020).
breast cancer (continued). "This occurrence likely facilitated the African American breast cancer associations regarding ATM c.2289T>C (p.F763L), BRCA2 c.2926_2927delinsAT (p.S976I) and RAD51D c.251T>A (p.L84H)." (PMID 32866190, 2020). "It is worth noting that several cancer types associated with pathogenic ATM mutations were all present in her family: three gastric cancer cases, two breast cancers, two pancreatic cancers and three colon cancers." (PMID 32756499, 2020). "For example, mutations in the gene encoding ATM (ataxia telangiectasia mutated) can lead to the development of AT or breast cancer, while mutations in the gene encoding FUS (fused in sarcoma) cause ALS and sarcomas." (PMID 33584810, 2020). "Then, triptolide was reported to inhibit the double-stranded DNA damage response in breast cancer cells through post-transcriptional downregulation of ATM, which causes a reduction in the levels of γH2AX." (PMID 33330091, 2020). "In accordance with this, we identified three ATM pathogenic variants in the index-case with breast cancer, one of whom also developed an ovarian cancer." (PMID 32756499, 2020). "There were some early evidence for heterozygous mutant ATM carriers possessing higher risk for breast cancer." (PMID 32566127, 2020). "The variant c.4776+2T>C in ATM, previously reported in a breast cancer case, modifies a canonical splicing site, potentially resulting in a splicing disruption." (PMID 32756499, 2020). "Individuals carrying heterozygous pathogenic variants in ATM have a 33% cumulative lifetime risk for breast cancer by 80 years of age." (PMID 32733558, 2020). "Patients with mutations in the ATM gene have an increased likelihood of several types of cancer, including breast cancer, leukemias, and lymphomas." (PMID 33268790, 2020). "The direct relationship between the presence of ATM variants and the overall risk of contralateral breast cancer remains controversial, although the combination of radiotherapy and certain ATM missense variants appears to accelerate tumour development." (PMID 31935898, 2020). "As expected, in contrast to ATR, we observed that low ATM was linked to aggressive phenotypes in MYC overexpressed breast cancers, including in ER+ tumours." (PMID 30746633, 2019). "A systematic review and meta-analysis was then conducted to quantitatively estimate the effect of ATM rs1801516 on the risk of breast cancer patients to develop radiation-induced fibrosis or telangiectasia." (PMID 31756226, 2019). "Loss of one or both alleles of ATM results in an increased risk of cancer development, particularly haematopoietic cancer and breast cancer in both humans and mouse models." (PMID 31565865, 2019). "As regard to radiation fibrosis, the meta-analysis including 2783 breast cancer patients revealed a borderline significant association of ATM rs1801516, being the risk higher among carriers of the minor A allele (OR: 1.23; 95%CI: 1.00–1.51, P = 0.049)." (PMID 31756226, 2019). "Overexpression of miR-421 leaded to down-regulation of ATM and is associated with poor prognosis of breast cancer." (PMID 31857500, 2019). "Cox regression analysis for the association of ATM rs1801516 with radiation-induced late skin injuries (LENT-SOMA scales) in our cohort of breast cancer patients." (PMID 31756226, 2019). "A few studies have reported hypermethylation of repetitive elements within the body of ATM to be associated with breast cancer risk." (PMID 31101124, 2019). "For instance, themes of DNA repair and G2‐M checkpoint regulation are consistent with the known roles of BRCA1/BRCA2 and ATM proteins, which are established risk factors for breast cancer." (PMID 30872331, 2019). "Some clinical trials for ATM-deficient breast cancer is documented (ClinicalTrials.gov Identifier: NCT02264678; NCT03565991)." (PMID 30975222, 2019). "Association with a significantly augmented pCR rate was found in metformin-treated breast cancer patients that have a “favorable” C allele-containing ATM SNP rs11212617 genotype." (PMID 30984619, 2019).
breast cancer (continued). "Overall, 10 cohorts of breast cancer patients (total n = 2928) were included in the meta-analysis of ATM rs1801516 and risk of developing radiation-induced telangiectasia." (PMID 31756226, 2019). "Our study showed that there was an association between the rs189037 in ATM gene and lung cancer, breast cancer, and oral cancer." (PMID 30709340, 2019). "In the entire set of breast cancer patients, the genotype frequency distribution of ATM rs1801516 was in HWE (P = 0.50) and the minor A allele frequency was of 13.7%." (PMID 31756226, 2019). "After exposure to irradiation, breast cancer exosomes led to an increased phosphorylation of ataxia telangiectasia mutated (ATM), Histone H2AX and checkpoint kinase 1 (Chk1) in recipient cells indicating the induction of DNA damage repair responses." (PMID 30925921, 2019). "In contrast, ATM deficiency either in the germ-line or due to epigenetic mechanisms is well known to increase cancer risk and promote breast cancers." (PMID 30746633, 2019). "It was estimated that heterozygous carriers of ATM mutations have a twofold higher breast cancer risk." (PMID 30975222, 2019). "Peripheral blood DNA methylation at the known breast cancer susceptibility genes BRCA1 and ATM has been found to be associated with elevated breast cancer risk." (PMID 31636290, 2019). "Taken together, our findings indicated that ATM gene was a candidate gene in susceptibility to breast cancer in Han Chinese." (PMID 29691986, 2018). "There are a few studies regarding associations between breast cancer development and the ATM gene mutation in the Polish population." (PMID 29678143, 2018). "Mutation in the ataxia telangiectasia mutated (ATM) gene is another one that confers increased risk of breast cancer." (PMID 29686906, 2018). "First, this is an observational case–control association study, and our data cannot be used to prove the cause–effect relationship between ATM gene and breast cancer risk." (PMID 29691986, 2018). "The published data on the role of ATM as a marker of genetic susceptibility to breast cancer is rather inconsistent." (PMID 29433565, 2018). "Another variant, rs189037, in the promoter region of ATM gene was found to be a risk factor for breast cancer, which was in agreement with the findings of the present study." (PMID 29691986, 2018). "High ATM protein levels have been associated with radioresistance in primary glioma, chordoma, and breast cancer cells." (PMID 29845714, 2018). "The A allele of rs1801516, located at 11q22.3 in the coding region of the ATM gene showed a reduction in the risk of breast cancer by 0.6-fold." (PMID 29433565, 2018). "An additional 5.1% (95% CI: 2.4–8.5) are estimated to carry a pathogenic allele of a moderate-risk breast cancer susceptibility gene (i.e., ATM, BARD1, CHEK2, or NBN) bringing the total proportion of estimated carriers to 10.4% (95% CI: 6.5–14.9)." (PMID 29945567, 2018). "The association of ATM genetic variation with breast cancer has been widely evaluated in Western countries, whereas it was rarely reported in China." (PMID 29691986, 2018). "When taking the most common haplotype (G‐C‐G‐G) as the reference group, haplotypes A‐C‐G‐G and A‐C‐A‐A in ATM gene were significantly associated with 1.98‐fold and 6.04‐fold increased risk of breast cancer (95% CI: 1.36‐2.90 and 1.65‐22.08, respectively)." (PMID 29691986, 2018). "The ataxia telangiectasia mutated (ATM) gene is a moderate-risk breast cancer susceptibility gene; germline loss-of-function variants are found in up to 3% of hereditary breast and ovarian cancer (HBOC) families who undergo genetic testing." (PMID 29665859, 2018).